MMP9 (matrix metallopeptidase 9)
Diseases named in the same sentence as MMP9 in open-access papers (continued):
Sharing a sentence is not in itself a finding about the gene and the disease.
coronary artery disease (continued). "A total of 90 patients with coronary artery disease (61% men, 58 ± 12 years), including 60 patients with STEMI and 30 patients with SIHD, were assessed within 24 h of admission, by measuring serum microRNAs, and serum MMP-1 and MMP-9." (PMID 39194717, 2024). "Unlike serum Gal-1 levels in coronary artery disease, serum MMP9 levels in coronary artery disease patients were significantly higher." (PMID 38192129, 2024). "A statistically significant difference in the activity of the MMP-9 gene was also observed between smokers and non-smokers with coronary artery disease and heart failure (p = 0.035)." (PMID 38540214, 2024). "This contradictory conclusion also indicated that we remained not fully understand the complexity of MMP-9 mechanisms of action in ischemic heart disease." (PMID 35410418, 2022). "Several different pro-inflammatory cytokines such as IL-6, matrix metalloproteinase-9 (MMP-9), and tumor necrosis factor-α (TNF-α) are each associated with coronary heart disease risk independent of conventional risk factors." (PMID 33479786, 2021). "As one of the highest incidences of CVDs, coronary artery disease links with more than 20 targets in this T-cD network, such as VCAM1 and ICAM1 (reported to increase in dysfunctional endothelial cells), MMP9, MMP3, and MMP2 (being influencing factors in cardiac fibrosis)." (PMID 29861771, 2018). "Moreover, in the group of overweight/obese patients with coronary artery disease and heart failure, a significantly higher transcriptional activity of the metalloproteinase 9 (MMP-9) gene was found compared to patients not burdened with this risk factor." (PMID 38540214, 2024). "Thus, the purpose of this study was to compare the plasma NGAL, MMP-9, IL-1β, and hs-CRP levels in different clinical presentations of coronary heart disease (CHD) and to evaluate the relationship between those biomarkers and the severity of coronary stenosis in patients without kidney disease." (PMID 31387110, 2019). "However, no changes in MMP9 activity were detected after FO supplementation in patients with coronary heart disease." (PMID 22621246, 2012). "Although the detection of NGAL and its complex with MMP-9 in systemic circulation seems reasonable, no studies of NGAL and MMP-9/NGAL in sera are currently available with the exception of two recent publications on coronary artery disease and polycystic ovary syndrome." (PMID 19889214, 2009). "In one study, ST-elevation myocardial infarction (STEMI) patients showed higher serum MMP-9 and MMP-9/TIMP-1 values compared to subjects without coronary artery disease (CAD), but they had no prognostic value in a 2-year follow-up." (PMID 29349668, 2018). "Therefore, we investigated whether salivary levels of MMP-9 and MPO corresponded to plasma levels in patients with coronary artery disease (CAD), both at rest and after acute physical exercise." (PMID 30726210, 2019). "We showed that diabetic patients with coronary artery disease presented significantly higher plasma levels of MMP-2, but not MMP-9, than nondiabetic counterparts." (PMID 28770228, 2017).
Arthritis (114 papers, 2005 to 2026). Inflammation of a joint. "The overexpression of matrix metalloproteinase-9 (MMP-9) has been implicated in the pathogenesis of various inflammatory disorders, including arthritis, cancer metastasis, and cardiovascular diseases." (PMID 40565127, 2025). "In the present study with LB, we chose to follow the changes in levels of MCP-1 and MMP-9 caused by arthritis." (PMID 36615489, 2022). "MMP9 encodes a matrix metallopeptidase that degrades type IV and V collagens, and is implicated in arthritis and metastasis." (PMID 22432004, 2012). "Matrix metalloproteinase 9 (MMP-9) is a protease responsible for remodeling extracellular matrix, and is associated with pathology in diverse inflammatory diseases including arthritis, cardiovascular diseases, pulmonary diseases, cancer, systemic lupus erythematosus, and SS." (PMID 30423938, 2018). "MMP-2-deficient mice show severe arthritis, whereas MMP-9-deficient mice exhibit mild arthritis." (PMID 28441353, 2017). "Reduced RANKL and MMP-9 expression may limit the bone destruction associated with arthritis by decreasing IL-17 expression." (PMID 27184722, 2016). "Targeting MMP-9 inhibition by pharmacological approaches could have clinical interventions in the treatment of bone loss diseases, such as arthritis and aseptic loosening." (PMID 24502696, 2014). "Moreover, PC downregulated the expression of PLA2G4A (−1.61-fold change), PLAUR (−1.94-fold change), and MMP9 (−1.91-fold change), all of which have been previously implicated in the pathogenesis of arthritis." (PMID 23936839, 2013). "In addition, TwHF extracts contained novel inhibitors of MMP including MMP9 thus might have therapeutic potential in arthritis and other conditions associated with increased MMPs like IgAN." (PMID 34977095, 2021). "MMP-2 knockout mice showed significantly increased, while MMP-9-deficient ones significantly reduced severity of arthritis in comparison with their wildtypes, suggesting a protective and a deleterious role of these enzymes in collagen antibody-induced arthritis, respectively." (PMID 30949048, 2019). "Their potential lies in attenuating prostaglandin-driven MMP-9 induction in conditions like arthritis, cancer, or vascular inflammation, thereby limiting tissue degradation without directly targeting the catalytic site." (PMID 41304763, 2025). "MMP-9 plays roles in inflammatory responses, wound healing, and angiogenesis, as well as in the pathogenesis of cancer, metastasis formation, arthritis, cardiovascular diseases, and more." (PMID 39858466, 2025). "In our study, we observed that DHA effectively reduced arthritis scores and joint swelling, and effectively inhibited the secretion of cytokines IL-17, MMP9, TRAP, and CTSK." (PMID 39257420, 2024). "MMP2 and MMP9 are enzymes that facilitate the restructuring of the ECM and have been implicated in the pathogenesis of arthritis." (PMID 39028255, 2024). "Ameliorated the underlying inflammatory response of carrageenan-induced arthritis, which enabled it to be a therapeutic drug for treating arthritis via regulating TNF-α/COX2/MMP9." (PMID 36757520, 2023). "MMPs such as MMP2, MMP3, and MMP9 are up-regulated in arthritis, leading to damage to bones and cartilage of joints via activation of IL1β, TNFα, and many other cytokines." (PMID 37765197, 2023). "High levels of ROS also promote collagen degradation by stimulating MMP activity, and PLD significantly alleviated the symptoms of collagen-induced arthritis in mice by reducing MMP9 activity." (PMID 36378815, 2022). "The expression of MMP9 has been detected in tumor invasion, inflammation, arthritis, liver I-R injury, and liver transplantation, all of which require disruption of the basement membrane." (PMID 34261545, 2021). "CEL-PRNPs were shown to efficiently target both inflammatory macrophages and OCs after responding to MMP9 in the inflammatory microenvironment of arthritis." (PMID 33846342, 2021).
Arthritis (continued). "For Matrix Metallopeptidase 9 (MMP9) the enzyme encoded by this gene degrades type IV and V collagens and is involved in the breakdown of the extracellular matrix during arthritis or metastasis." (PMID 34943943, 2021). "Like other MMP family members, MMP9 is involved in disease processes such as metastasis and arthritis, as well as in the degradation of extracellular matrix components in normal processes such as reproduction and tissue remodeling." (PMID 34587931, 2021). "FMRP is known to regulate multiple connective tissue pathways including elastin, actin, and matrix metalloproteinase (MMP9), a class of enzymes involved in bone development, wound healing, and pathology such as arthritis and intracerebral hemorrhage." (PMID 35126193, 2021). "MMP-9 promotes the migration and invasion of FLS in collagen-induced arthritis in mice, whereas MMP-3 causes FLS to migrate to adjacent cartilage and induces articular cartilage degradation." (PMID 32568738, 2020). "Unlike MMP-2 KO mice, MMP-9 KO mice showed reduced levels of Antibody-Induced Arthritis, indicating that MMP-9 enhances arthritis in this model." (PMID 32982752, 2020). "In vivo, the inhibition of TRAF6 using mice-specific TRAF6 siRNA inhibit serum anti-collagen II antibodies, MMP-1, MMP-3, and MMP-9, thereby reducing the severity of arthritis and joint inflammation." (PMID 33294443, 2020). "Expression of MMP-2 (gelatinase A) and MMP-9 (gelatinase B) are also elevated in arthritis, but interestingly they have distinct roles in RA." (PMID 30949048, 2019). "Immunohistochemical analysis of the paw sections showed that the reduction of the arthritis-induced MMP-9 and p-p65 expression upon PFS administration occurred in the synovial membrane, and also in the bone pannus." (PMID 28463993, 2017). "The specific role of MMP-9 in B. burgdorferi invasion and inflammatory response under in vivo conditions is assessed by infecting MMP-9−/− mice and comparing to wild-type mice in regards to bacterial burden, arthritis, and carditis." (PMID 28270812, 2017). "Because abnormal expression of mmp9 and mmp13 occurs in human diseases such as cancer, arthritis and cardiovascular disorders, small molecule inhibitors specific to MMP9 and MMP13, respectively, or to both MMP9 and MMP13 were available." (PMID 28158191, 2017). "Infected MMP-9−/− mice develop less arthritis relative to wild-type mice with an unexpected similarity in cytokine and chemokine expression, indicating that the ability of MMP-9 to modulate an inflammatory response is independent of B. burgdorferi infection." (PMID 28270812, 2017). "MMP9 has been shown to be critical for the development of arthritis as MMP9 KO mice develop less inflammation and joint destruction in the serum transfer model." (PMID 28724439, 2017). "Constitutively overexpressed cathepsin K in mice leads to marked proliferative synovitis and destruction of articular cartilage and bone, and MMP-9 gene deletion mice are significantly less vulnerable to arthritis in mice experiment." (PMID 28463993, 2017). "We also tested in SIC the levels of MMPs (MMP-2 and MMP-9), one of the key mediators of tissue damage in arthritis." (PMID 23762133, 2013). "Several other members including MMP-9 have been localized to cartilage or synovium in the arthritis patients." (PMID 21854562, 2011). "APC reduced the MMP-9 levels in fibroblasts and monocytes of arthritis patients, but up-regulated and activated MMP-2." (PMID 20356362, 2010). "In this context, we have recently shown that MMP9 mediates hypernociception that developed during antigen-induced arthritis, a model in which IL-1β also plays a role." (PMID 20920345, 2010). "By zymography, MMP-9 activity was increased in joint washouts from arthritic C57BL/6 mice with increasing arthritis severity." (PMID 20196869, 2010).
Arthritis (continued). "We thus examined the levels of MMP-9 in SF from 19 patients with different forms of arthritis, including RA, OA, chronic juvenile arthritis, and other forms of arthritis, and compared them with the levels of the NPA." (PMID 16859524, 2006). "For pro-MMP-9, we detected by zymography an increased protein content in knee joints during the development of experimental arthritis." (PMID 15642138, 2005). "Itoh and colleagues showed in the model of antibody-induced arthritis that MMP-9 knockout mice displayed milder arthritis than their wild-type littermates." (PMID 15642138, 2005). "Serum concentrations MMP-1, MMP-3, and MMP-9, acutely adapt to mechanical loading, with rapid increases at the beginning of physical activity followed by a fairly rapid stabilization thereafter; moreover, MMP-2, MMP-3, and MMP-9 are highly expressed in patients afflicted by arthritis." (PMID 36835076, 2023). "By weakening the extracellular matrix covering the joints or inducing inflammatory factors, MMP-9 may worsen arthritis." (PMID 36297105, 2022). "Also, the increase in MMP9 level plays a critical role in the development of arthritis, inflammatory disorders, cancer, pulmonary diseases, cardiovascular disorders and dry eye syndrome." (PMID 35440028, 2022). "However, MMP-9 increases in synovial fluid of SpA patients, MMP-9 activity correlates with SpA severity, and it participates in the pathogenesis of arthritis." (PMID 36700196, 2022). "Neutrophil granules contain high levels of MMP-9, produced by invading cells of the monocyte/macrophage lineage, which can dissolve collagen types I and II and degrade gelatin, an excessive production of which eventually leads to arthritis." (PMID 36297105, 2022). "Here the authors design celastrol-loaded nanoparticles that release a payload in response to MMP9 cleavage and show these NPs are effective at inducing apoptosis of human macrophages in vitro and a therapeutic effect with an adjuvant-induced arthritis model in rats." (PMID 33846342, 2021). "MMP-9 has been shown to play a potentially essential role in the dissemination of B. burgdorferi as well as play a role in the development of some of the signature manifestations of Lyme disease, including arthritis and carditis." (PMID 34827233, 2021). "In addition, a high level of IL33 induces the expression of inflammatory cytokines IL1-β, IL6, IL13, and IL17, as well as matrix metalloprotease- (MMP-) 3 and MMP-9 in arthritis." (PMID 34305456, 2021). "Since MMP9 is secreted through inflammatory cells, it could increase arthritis by degrading anti-inflammatory factors, activating inflammatory factors, or promoting the migration of inflammatory cells." (PMID 33297427, 2020). "Based on the IPA analysis BmA pre-exposure before LPS E. coli re-stimulation affected several pathways like granulocyte and agranulocyte adhesion and diapedesis (PPBP/CXCL7, PECAM1, CCL20, CXCL5, CXCL6, MMP9), IL-17 in psoriasis, arthritis and signaling in airway cells (CCL20, CXCL5, CXCL6)." (PMID 30796272, 2019). "Further, arthritis significantly increased MMP-9 in plasma on day 14 (AA vs. CO, *** p < 0.001)." (PMID 29113115, 2017). "Elevation of both circulating MMP-9 and WBC count have been considered risk factors or biomarkers for cardiovascular disease, COPD, arthritis and metabolic syndrome, all of which are associated with subclinical inflammation and are promoted by smoking." (PMID 23825535, 2013). "In contrast, the absence of Mmp-9 was associated with reduced severity of arthritis, indicating the need of Mmp-9 for the development of arthritis." (PMID 21190566, 2010). "MMP-9 level was increased more in early stages of arthritis than in later stages." (PMID 19883500, 2009). "Interestingly, Mmp13 and Mmp9 induction are also found in patients with arthritis; these individuals also have abnormal matrix, and could share the same pathogenetic mechanism." (PMID 28158191, 2017).
Arthritis (continued). "MMP-9 (92-96 kD gelatinase B) has been a member of gelatinase subfamily and considered to be involved in the cellular invasion of the basement membrane by cells (e.g. T cells, mononuclear phagocytes, synovial fibroblasts, and metastatic tumor cells) involved in arthritis and cancer." (PMID 24179443, 2013). "Joint swelling and the arthritis-related expression levels of IL-1β, IL-6, RANKL, MMP9, and OC-Stamp were strongly reduced, while Foxp3 was induced." (PMID 36003376, 2022). "Sixteen days after arthritis induction 57–60 kDa MMP isoform, 75 kDa MMP-2 and 92 kDa MMP-9, but at 30 days only 57–60 kDa isoform increased significantly in the ankle joint homogenates of both arthritic groups as compared to the non-arthritic controls." (PMID 30949048, 2019). "We found markedly increased levels of MMP9 and MMP13 in KLF2−/− mice compared to KLF2+/+ mice after induction of arthritis." (PMID 31426355, 2019). "An early upregulation of MMP-3 and MMP-9 activities has been described in TNF-overexpressing mice that develop arthritis, also implying that FLS activation is an early event in arthritis pathogenesis and supporting our findings." (PMID 30466479, 2018). "An example of such a disease is arthritis, where MMP-2 is a disease suppressor whereas MMP-9 contributes to pathology." (PMID 28369077, 2017). "Differently, it was previously demonstrated that the MMP-9 levels correlated with synovial fluid VEGF levels and with the pattern of vascularity found in the synovial membrane tissue of patients with arthritis." (PMID 22900195, 2012). "Given that MIF regulates the expression of MMPs during pathological inflammatory responses such as arthritis, we investigated the possible involvement of MMP-2 and MMP-9 in T. gondii-induced MIF-mediated ileitis." (PMID 21977228, 2011). "It has also been reported that cytokine released from arthritis-affected joints, inparticular IL-1β, can stimulate the secretion of metalloproteinases (MMPs),especially MMP-2 and MMP-9, in endothelial and vascular smooth muscle cells, whichmay reduce the action of vasoconstrictor agonists." (PMID 38775546, 2024). "For arthritis, iguratimod has been demonstrated to inhibit serum MMP-1 and MMP-3 of RA patients; while in bleomycin-induced interstitial lung disease, iguratimod increased the level of MMP-9 of lung tissues." (PMID 37596660, 2023). "MMP-9, which is increasingly expressed in arthritis, degrades the noncollagen matrix components of the cartilage." (PMID 35003293, 2021). "MMP9 is a matrix metalloproteinase involved in the degradation of the ECM in physiological processes such as tissue remodeling and embryonic development, as well as in pathological processes such as the progression of arthritis and cancer metastasis." (PMID 32847597, 2020). "Furthermore, a function study reported that the S100A8 stimulation in chondrocytes induces upregulation of mRNA levels of MMP-2, MMP-3, MMP-9, and MMP-13 and ADAMTS-4 and ADAMTS-5 in experimental murine arthritis, which is similar to our findings." (PMID 31815654, 2019). "Moreover, CypA blockade counteracts the CypA-dependent MMP-9 secretion in monocytes/macrophages and remarkably reduces the inflammatory cell number, MMP-9 production, and cartilage erosion in mice arthritis model." (PMID 30949512, 2019). "The matrix metalloprotease MMP9 expression is found elevated in arthritis and this enzyme degrades noncollagen matrix component of the joint." (PMID 29850558, 2018). "Expression of MMP2, MMP9, and MMP13 genes, which are related to the endochondral ossification pathway and bone remodeling, was also increased in the arthritic paw up to day 8 after arthritis induction." (PMID 26801240, 2016). "So MDC and MMP-9 may be involved in the pathogenesis of lupus nephritis and seemed to be markers of renal damage, and MDC may be involved in the pathogenesis of arthritis and seemed to be a new sensitive marker of article damage." (PMID 26430407, 2015).